RNU6-1289P (RNA, U6 small nuclear 1289, pseudogene)
Gene: Small nuclear RNA gene on chromosome 18 (26,366,301 to 26,366,406, reverse strand). Ensembl gene ENSG00000207160.
Homologues: Orthologues: chimpanzee U6 (100% identical), macaque U6 (97% identical), pig U6 (90% identical), mouse Gm22345 (82% identical), dog U6 (78% identical), guinea pig U6 (73% identical). Paralogues in human: RNU6-188P (92% identical), RNU6-310P (92% identical), RNU6-1145P (90% identical), RNU6-1316P (90% identical), RNU6-15P (90% identical), RNU6-211P (90% identical), RNU6-477P (90% identical), RNU6-1081P (89% identical), RNU6-116P (89% identical), RNU6-20P (89% identical), RNU6-35P (89% identical), RNU6-1 (88% identical), and 1290 more.